TLR7 (toll like receptor 7)
Diseases named in the same sentence as TLR7 in open-access papers (continued):
Sharing a sentence is not in itself a finding about the gene and the disease.
Arthritis (16 papers, 2012 to 2025). Inflammation of a joint. "We found that TLR7-rs3853839 genotype GG was associated with arthritis (CC vs GG, P = 0.01, OR 0.10, 95% CI 0.02 to 0.60)." (PMID 36439744, 2022). "A recent study also showed that TLR7 deficiency led to K/BxN serum-induced arthritis reduction by imparing interferon regulatory factor 5 (IRF5) mediated IL-1β and IL-6 generation in macrophages and synovial fibroblasts, respectively." (PMID 34950033, 2021). "A recent study showed that TLR7 deficiency alleviated K/BxN serum-induced arthritis by imparing interferon regulatory factor 5 (IRF5) mediated IL-1β and IL-6 produced by macrophages and synovial fibroblasts, respectively." (PMID 34950033, 2021). "The amelioration of arthritis by mianserin and TLR7 deficiency both corresponded with a reduction in IL-17 responses, histological and clinical scores, and paw swelling." (PMID 22691272, 2012). "Synovial pDCs can produce robust IFN-α, and persistent arthritis has been induced by intra-articular transfer of IFN-I-producing DCs; conversely, in other models, pDC deficiency exacerbates arthritis, and disease activity improves with pDC mobilization/activation via TLR7 agonists." (PMID 41301504, 2025). "Recently, X-linked TLR7 polymorphism has been confirmed to be associated with arthritis." (PMID 35508687, 2022). "Also, different TLR7 rs3853839 genotypes and alleles were associated with other clinical manifestations such as arthritis, oral ulcer, and Thrombocytopenia." (PMID 36439744, 2022). "Initiation of CIA requires CFA, which is a mixture of mineral oil and heat-inactivated MTB; thus, it was possible that TLR7 deficiency may haveprevented the induction of arthritis." (PMID 22691272, 2012). "Patients with arthritis demonstrated higher frequencies of TLR7+ intermediate monocytes and elevated Epidermal growth factor (EGF) levels, whereas those with edema exhibit increased Vascular endothelial growth factor (VEGF) levels." (PMID 41012652, 2025). "Conversely, enhancing PDC recruitment and activation to arthritic joints by topical application of the Toll-like receptor 7 (TLR-7) agonist imiquimod significantly ameliorated arthritis." (PMID 38068720, 2023). "In vivo PCR microarray indicated that EFL2 exerted anti-arthritis bioactivity by suppressing TLR7 mediated signaling pathway." (PMID 34950033, 2021). "DNA, RNA and TLR7/9 activation are required to generate α-hnRNP-specific B cells and this complex induced RA in a pristane-induced arthritis model of RA." (PMID 34521462, 2021). "TLR7-/- mice developed a mild arthritis, where the clinical score and paw swelling were significantly compromised in comparison to the control group." (PMID 22691272, 2012). "Also, TLR7 rs3853839 G risk allele was related to numerous clinical signs of SLE, including arthritis, malar rash, oral ulcer, photosensitivity, Thrombocytopenia, and pericardial effusion, according to." (PMID 36439744, 2022). "Moreover, we determined its inhibitory role on TLR7 mediated signaling pathways and elucidated its anti-arthritis mechanisms both in vivo and in vitro." (PMID 34950033, 2021). "Besides the evidence in RA patients, TLR7 is also reported to implicate in the pathogenicity of both collagen-induced arthritis and STA model." (PMID 34950033, 2021). "We questioned whether the reduced arthritis observed in TLR7-/- animals was due to a failure to elicit a robust immune response to Mycobacterium tuberculosis (MTB), the active ingredient in the adjuvant used in the CIA model." (PMID 22691272, 2012). "Low-dose activation of TLR7 with a small synthetic ligand has been shown to induce tolerance of TLR2, 7, and 9 signaling and to suppress disease in a serum transfer model of arthritis." (PMID 22691272, 2012). "Similarly, patients with arthritis exhibited significantly higher TLR7 MFI in intermediate monocytes than those without arthritis." (PMID 41012652, 2025).
Arthritis (continued). "HnRNPs may also induce pro-inflammatory cytokines, relevant for arthritis development in rats, which involve TLR7 and TLR9 but not TLR4." (PMID 34521462, 2021). "Despite the consistent success of selective inhibition of TLR ligation in animal models, DV-1179 (dual TLR7/9 antagonist) failed to achieve pharmacodynamic effectiveness in SLE, and NI-0101 (mAb against TLR4) failed to improve arthritis in RA." (PMID 38255243, 2024).
colorectal cancer (16 papers, 2014 to 2025). A primary or metastatic malignant neoplasm that affects the colon or rectum. "In this study, the synergistic effects of gene-targeting HIF-1α siRNA combined with Toll-Like Receptor 7 agonist on TME remodeling were investigated in a mouse model of colorectal cancer (CRC)." (PMID 39614894, 2024). "In this study, we have demonstrated that i.p administration of the TLR7 agonist Loxoribin leads to tumor regression in two tumor models, i.e. a colorectal cancer model and a LLC tumor model." (PMID 25593198, 2015). "To determine the role of TLR7 in cancer, we initially investigated its effect on two tumor models in vivo, i.e. a colorectal cancer model and a Lewis Lung Cancer (LLC) tumor model." (PMID 25593198, 2015). "The data demonstrate that systemic administration of the novel TLR7 agonist DSR-6434 in combination with IR primes an antitumor CD8+ T-cell response leading to improved survival in syngeneic models of colorectal carcinoma and fibrosarcoma." (PMID 24390981, 2014). "MicroRNA-21-5p (miR-21) is highly expressed in colorectal cancer-derived sEVs, polarizes hepatic macrophages to an interleukin 6 (IL-6) producing phenotype via toll-like receptor 7 (TLR7), induces the formation of an inflammatory microenvironment, and promotes CRC liver-specific metastasis." (PMID 36552835, 2022). "Through the TLR7 signalling pathway, liver macrophages polarize to a pro‐inflammatory phenotype and produce cytokines such as IL‐6, thus generating a pre‐metastatic niche for colorectal cancer in the liver." (PMID 33169503, 2020). "Moreover, our results indicated that both TLR7 and TLR8 expression is associated with tumor progression in patients with colorectal cancer and reduced tumor-specific survival among patients with high TLR7 and TLR8 expression in their cancer cells." (PMID 26134824, 2015). "In summary, we developed a sequential pH/GSH-responsive triblock polymeric nanomicelle system that codelivers the chemotherapeutic drug CPT and the TLR7/8 agonist IMDQ, inducing amplified chemoimmunotherapy of colorectal cancer." (PMID 35953798, 2022). "Our previous study indicated that endosomally expressed TLR7 and TLR8 are associated with tumor progression in colorectal cancer and reduced tumor-specific survival amongst patients with high TLR7 and TLR8 expression in colorectal cancer cells." (PMID 26134824, 2015). "We previously reported that TLR7 and TLR8 expression is upregulated in tumor cells of patients with colorectal cancer." (PMID 26134824, 2015). "In some cases, TLR7 stimulation of T cells alone is sufficient for anti-tumor responses: nanoparticle delivery of R848 to CD8+ T cells results in increased anti-tumor immunity and prolonged survival in a murine colorectal cancer model." (PMID 31615993, 2019).
genital warts (16 papers, 2012 to 2024). "Primarily known as a treatment for certain skin conditions like actinic keratosis, superficial basal cell carcinoma, and genital warts due to its ability to stimulate the immune response, R837 also acts as a TLR7 agonist." (PMID 38006036, 2023). "Imiquimod, which is used for superficial SCC and BCC and genital warts, is a ligand for both TLR7 and NLRP3, therefore inducing both IL-1 and interferon." (PMID 27768771, 2016). "IMQ activates the Toll-like receptors 7 and 8 (TLR7/8), and is used to treat genital warts in patients." (PMID 26818707, 2016). "Currently, a 5% imiquimod cream targeting TLR7 is approved for treatment of HPV-induced genital warts, whereas treatment of genital HSV infection with a resiquimod cream targeting TLR7/8 has been discontinued." (PMID 23435233, 2013). "Topical administration of the TLR7 agonist imiquimod elicits a potent type I interferon response and has efficacy for the treatment of genital warts, VIN and CIN, presumably by enhancing and targeting spontaneous immunity and counteracting a suppressive microenvironment." (PMID 25560237, 2015). "The TLR7 agonist imiquimod has been approved by the FDA for topical treatment of actinic keratosis and genital warts as early as in 1997." (PMID 37063284, 2023). "IMQ activates the toll-like receptor-7/8 (TLR-7/8), which is used to treat genital warts in patients." (PMID 29619073, 2018).
Thrombocytopenia (16 papers, 2011 to 2025). A reduction in the number of circulating thrombocytes. "In patients with pSS‐associated thrombocytopenia, B cells showed increased expression of IL‐8 and molecules from the TLR7 pathway." (PMID 40656544, 2025). "Another significant association was detected, where TLR7-rs3853839 G allele was associated with Thrombocytopenia (C vs. G, P < 0.0001 OR 0.04, 95% CI 0.01–0.16)." (PMID 36439744, 2022). "Compared to that in control patients, the expression of interleukin (IL)-8 and TLR7 pathway molecules in B-cells was higher in patients with pSS-associated thrombocytopenia." (PMID 33767707, 2021). "The findings of this study indicate that TLR7 and its downstream signaling molecules are strongly expressed in patients with pSS-associated thrombocytopenia." (PMID 33767707, 2021). "These and other ssRNA viruses, which signal through TLR7, are associated with thrombocytopenia, giving rise to suppositions that platelet TLR7 mediates viral sensing and/or host defense mechanisms." (PMID 25566264, 2014). "TLR7 (Toll-like receptor 7) contributes to thrombocytopenia associated with pSS as manifested by the relatively higher expression level of hsa_circ_0008301 in patients with thrombocytopenia." (PMID 39062113, 2024). "TLR7 pathway regulation might be a potential new treatment option for patients with pSS-associated thrombocytopenia." (PMID 33767707, 2021). "We further investigated whether intervention of the TLR7 pathway may affect platelet count and induce pSS-associated thrombocytopenia-like manifestations in pSS model mice." (PMID 33767707, 2021). "In this study, we showed that pSS-associated thrombocytopenia elicited a significantly stronger inflammatory response related to the TLR7 signaling pathway activation than in general patients with pSS, as indicated by increased inflammation, cytokine secretion, and NF-κB activity." (PMID 33767707, 2021). "Our findings suggest that pSS-associated thrombocytopenia might be a subset of pSS characterized by a systemic inflammatory state, which might be induced by stronger TLR7 pathway activation." (PMID 33767707, 2021). "Conclusion: pSS-associated thrombocytopenia may be a subset of the systemic inflammatory state as the TLR7 signaling pathway was upregulated in B cells of patients with pSS-associated thrombocytopenia, and activation of the TLR7 pathway led to a thrombocytopenia phenotype in NOD mice." (PMID 33767707, 2021). "Therefore, strategies inhibiting the TLR7 pathway may benefit patients with pSS-associated thrombocytopenia, which should be a major focus for further investigation in the clinic." (PMID 33767707, 2021). "Through high‐throughput sequencing of B cells, the importance of the TLR pathway was elucidated, and the involvement of the TLR7 signaling pathway in thrombocytopenia related to pSS was investigated." (PMID 40656544, 2025). "The role of TLR7 in platelet production has not been extensively studied, but in patients with primary Sjogren’s syndrome-related thrombocytopenia, TLR7 and its downstream signaling molecules are strongly expressed." (PMID 36674552, 2023). "Being a downstream signaling molecule of the TLR7 pathway, increase in IL-8 can reflect the activation of the TLR7 pathway and the pathogenesis leading to thrombocytopenia in pSS." (PMID 33767707, 2021). "Compared with that in the control group, the expression of TLR7, MyD88, IRAK4, and TRAF6 increased significantly in the B cells of patients with pSS associated thrombocytopenia (p < 0.05)." (PMID 33767707, 2021). "Serum, peripheral blood, bone marrow, and submandibular glands were collected for thrombocytopenia and TLR7 pathway analysis." (PMID 33767707, 2021). "Here, we show that overactivation of the TLR-7 pathway of viral recognition by Resiquimod treatment of CFN mice induces severe thrombocytopenia and internal bleeding, which manifests most prominently as hemorrhagic myocarditis." (PMID 31324689, 2019).
Thrombocytopenia (continued). "The mice harboring D34A mutation on Unc93b1 (D34A mice) suffer from systemic inflammation, such as hepatitis, thrombocytopenia, splenomegaly and nephritis, depending on the excessive response of TLR7." (PMID 29988708, 2018). "Even if the administration of A94B10 was started when D34A mice had already developed thrombocytopenia, the anti-TLR7 mAb was still effective." (PMID 29988708, 2018). "Notably, in the same study activation of the TLR7 pathway in NOD mice led to thrombocytopenia and increased IL-1β and IL-8 levels both in the serum and submandibular glands compared to control groups." (PMID 36389822, 2022). "However, despite its role in thrombocytopenia, platelet TLR7 activation improved mice survival, as platelet–granulocyte aggregate formation enabled ECMV clearance." (PMID 34360659, 2021). "Our present data demonstrated the increased expression of the TLR7 pathway molecules in B cells of patients with pSS-associated thrombocytopenia compared to pSS patients without thrombocytopenia." (PMID 33767707, 2021). "Interestingly, in contrast to TLR7-deficient mice, wild-type mice infected with the encephalomyocarditis virus (EMCV) or exposed to the TLR7 agonist loxoribine underwent thrombocytopenia (more pronounced upon loxoribine exposure)." (PMID 34360659, 2021). "In addition, complex immunopathological pathways may stand in the background, like TLR7 signaling pathway and P-selectin autoantibodies, which link to thrombocytopenia is known in pSS." (PMID 40530052, 2025). "A study with 3 patients with pSS-associated thrombocytopenia, 3 pSS patients with normal platelets and 3 healthy controls, revealed increased TLR7 and IL-8 expression in B cells of pSS-associated thrombocytopenia compared to pSS patients without thrombocytopenia or healthy controls." (PMID 36389822, 2022). "Thus, we detected TLR7 and its downstream signaling molecules in B cells of patients with pSS-associated thrombocytopenia compared to pSS patients without thrombocytopenia in the validation cohort." (PMID 33767707, 2021). "We also demonstrated that TLR7 activation could induce thrombocytopenia in a mouse model of pSS." (PMID 33767707, 2021). "A previous bioinformatics analysis and validation study in patients with pSS revealed the TLR7 pathway as the most canonical pathways in pSS-associated thrombocytopenia compared to pSS patients without thrombocytopenia and healthy controls in the validation cohort." (PMID 33767707, 2021). "Notably, TLR7 plays a critical role in ongoing platelet–leukocyte aggregate (PLA) formation and development of thrombocytopenia in septic mice." (PMID 41301522, 2025). "The TLR7 signaling pathway was upregulated in patients with thrombocytopenia compared with that in patients without pSS." (PMID 33767707, 2021). "TLR7-stimulated mice also tended to have thrombocytopenia (~80% of mice), however, this was not overall significant since two resiquimod-treated NZM2410 mice had a thrombocytosis." (PMID 31998321, 2019).
colon carcinoma (15 papers, 2014 to 2026). "A mouse model study showed that a defect in TLR7 of pDCs is responsible for the aggravation of colitis-associated colon cancer and that TLR7 ligand can mitigate colitis-associated colon cancer." (PMID 36476317, 2022). "For instance, the administration of an anti-CD200R agonist (OX110) potentiated the anti-tumor effects of R848, a Toll-like receptor 7 (TLR7) agonist, and significantly reduced tumor volume and growth in colon carcinoma murine models." (PMID 38137547, 2023). "Loxoribin, a TLR7 agonist, inhibited tumor growth using xenograft models for both lung and colon cancer, both mediated by promoting CD4+ T cells and activating dendritic cells." (PMID 29190881, 2017). "Notably, TLR7 rs3853839 has been identified in one study as a predictive marker for cetuximab-based chemotherapy in colon cancer patients, highlighting its potential clinical relevance in treatment response." (PMID 39026223, 2024). "TLR7 agonists also act to promote T lymphocyte migration into the local tissue of colon cancer." (PMID 33982398, 2021). "We next moved to evaluatethe translational potential of p(Man-TLR7-PDS).To do so, we aimed to establish dose-dependent efficacy of the technologyin MC38 colon carcinoma." (PMID 36313164, 2022). "A recent study on animals with colon cancer, suggests that co-treatment with anti-CD200R and a Toll-Like Receptor 7 (TLR-7) agonist promotes the anti-tumor effects of myeloid cells within the TME." (PMID 32656079, 2020).